INS (insulin)
Diseases named in the same sentence as INS in open-access papers (continued):
Sharing a sentence is not in itself a finding about the gene and the disease.
Insulin resistance (continued). "In the stair descending group, bout 1 induced significant elevations of insulin, glucose and HOMA in plasma at day 2 post exercise, indicating insulin resistance probably due to the presence of muscle damage." (PMID 23437093, 2013). "Recent studies have demonstrated the presence of an unfolded protein response (UPR) in the liver and adipose tissue of insulin-resistant rodents, and counteraction of UPR has been shown to improve the insulin resistance in these animals." (PMID 23894352, 2013). "Cardiometabolic biomarkers including fasting insulin, glucose, blood lipids, HOMA-Insulin Resistance, and oral glucose tolerance were also measured." (PMID 23326600, 2013). "In the males, we have observed high insulin plasma levels and elevated HOMA-IR index, indicating peripheral insulin resistance." (PMID 26904613, 2013). "Although TNF-α levels in the circulation is positively correlated with insulin resistance, and neutralization of TNF-α improved the insulin sensitivity in rodents, clinical effects of TNF-α neutralization in humans are still controversial." (PMID 23781214, 2013). "More interestingly, H2S donor also reduced insulin resistance in HFD mice, but slightly decreased insulin sensitivity in normal chow mice." (PMID 24058499, 2013). "Insulin resistance status was estimated by the homeostasis model assessment of insulin resistance (HOMA-IR) and the quantitative insulin sensitivity check index (QUICKI)." (PMID 24171177, 2013). "Insulin resistance in type 2 diabetes can result in high phosphorylation of tau protein and the accumulation of Aβ peptide in brain indirectly via IDE or via insulin/insulin receptor signal pathway, leading to AD-like pathology and cognitive impairment." (PMID 24386004, 2013). "In order to determine the effect of IGFBP-3 on TNF-α-induced insulin resistance, adipocytes were infected with IGFBP-3 alone and in the presence of TNF-α and insulin." (PMID 23383064, 2013). "The decrease of GLUT-2 membrane receptors coupled with insulin resistance and beta cell dysfunction in ZDF rat can be commonly used to simulate the mechanism of human T2DM and test insulin sensitizers and other various agents." (PMID 23671868, 2013). "Another limitation is the insulin resistance, which was evaluated by HOMA-IR index or serum insulin levels, instead of the hyperinsulinemic-euglycemic clamp." (PMID 23894289, 2013). "Serum insulin, glucose and the HOMA-IR index also increased, suggesting a tendency towards insulin resistance." (PMID 23575345, 2013). "Individuals with IFH had higher FPG, liver insulin resistance (evaluated by HOMA-IR and ISIm) and better early phase insulin secretion ability (evaluated by ΔI30/ΔG30) compared to subjects with IPH." (PMID 23990951, 2013). "Insulin resistance was evaluated with HOMA-IR, which was calculated for all subjects by the following formula: fasting serum insulin (μU/mL) x fasting plasma glucose (mg/dL)/405." (PMID 23825975, 2013). "Accordingly, men with OSA and HWC had higher hepatic insulin resistance as reflected by higher HOMA-IR levels, and lower global insulin sensitivity as reflected by lower levels of ISI Matsuda compared to apneic men with LWC." (PMID 23951064, 2013). "To investigate the role of endogenous CSE/H2S in insulin resistance, we treated mice with PAG or GYY4137 for 13 week, then we assessed the insulin sensitivity." (PMID 24058499, 2013). "Fasting serum insulin and HOMA-IR were significantly higher in the overweight children, reaffirming the essential pathophysiological role of insulin resistance in the development of NAFLD." (PMID 23367495, 2013). "The levels of fasting insulin (FINS) and homeostatic model assessment insulin resistance (HOMA-IR) were higher in PCOS-IR patients than PCOS-NIR patients or healthy controls (p<0.05)." (PMID 23705014, 2013). "Women with AGT had higher levels of insulin resistance, as measured by HOMA-IR, and lower level of insulin sensibility, as measured by QUICKY, than NGT women." (PMID 24171177, 2013).
Insulin resistance (continued). "Under in vitro conditions of hormonal or fatty acid-induced insulin resistance, PMI5011 improves insulin signaling and reduces Atrogin-1 and MuRF-1 protein levels." (PMID 23437325, 2013). "HFD also increased the fasting blood glucose (FBG) and fasting insulin levels, and therefore insulin resistance as determined by the HOMA-IR insulin resistance index." (PMID 24376593, 2013). "Indeed, preclinical and clinical experiments showed that obese rodents and humans displayed leptin resistance that may directly contribute to the reduction of lipid oxidation in insulin-sensitive organs, leading to accumulation of lipids and insulin resistance." (PMID 24455420, 2013). "In order to investigate the direct involvement of FA1 in stimulating insulin resistance in myotubes, we studied the effect of soluble FA1 on different parameters of insulin sensitivity in cultured myotubes established from lean subjects." (PMID 23577002, 2013). "After high fat diet for 14 days, there was a significant increase in blood glucose levels at every time point of OGTT, AUC, fasting insulin levels, and HOMA-IR, implying that these rats had developed obvious insulin resistance." (PMID 24371833, 2013). "Subjects with IFG have increased hepatic glucose output and early dysfunction of insulin secretion, while subjects with IGT have moderate-to-severe insulin resistance in the muscle." (PMID 23819126, 2013). "Body mass index, insulin/proinsulin ratio and (HOMA) insulin resistance and beta cell function were also calculated." (PMID 23497407, 2013). "The insulin sensitivity index KITT was calculated and a lower KITT suggests decreased insulin sensitivity or insulin resistance." (PMID 23675970, 2013). "In mouse C2C12 myotubes, AMPK activation potentiated insulin action by reducing IRS-1 serine phosphorylation, while reduced muscle AMPK activity has been reported to aggravate muscle insulin resistance following a high-fat diet over 30 weeks." (PMID 23861559, 2013). "The homeostasis model assessment estimate of insulin resistance (HOMA-IR) and early insulin release index (IRI) were calculated to evaluate insulin sensitivity and early β-cell secretion." (PMID 24137224, 2013). "Close systematic monitoring of fasting and postprandial glycemia and fasting insulin determinations, HOMA-insulin resistance and HOMA β-cell function were performed." (PMID 23557386, 2013). "Most participants were overweight or obese or had waist circumferences greater than the cutoffs used to indicate risk of metabolic syndrome (94 cm in men and 80 cm in women), and fasting insulin was elevated as was HOMA-IR, which indicated insulin resistance." (PMID 23964054, 2013). "We further evaluated glucose homeostasis by calculating the homeostasis model of insulin resistance (HOMA-IR) index and by performing glucose and insulin tolerance tests (ITTs)." (PMID 23562076, 2013). "In the current study, our data demonstrate that overexpression of MFN2 significantly restored insulin sensitivity and reduced the levels of BG and plasma insulin in rats, suggesting MFN2 as a potential therapeutic target in insulin resistance." (PMID 23815800, 2013). "Accordingly, apneic men with high-waist circumference had higher hepatic insulin resistance as reflected by higher HOMA-resistance index, and lower global insulin sensitivity as reflected by lower insulin sensitivity index of Matsuda (derived from OGTT)." (PMID 23951064, 2013). "These animals had significantly elevated blood glucose and insulin levels, leading to an increased homeostatic model assessment of insulin resistance index (HOMA-IR), indicative of whole-body insulin resistance." (PMID 23612947, 2013). "The insulin level also increased in DIO mice, but to a higher degree, suggesting insulin resistance was induced in the obese model and can be recovered by CR or CR plus exercise." (PMID 23762877, 2013).
Insulin resistance (continued). "Moreover, hyperglycemia and hyperinsulinemia are observed in the offspring of mothers exposed to a high fat (HF) diet and are associated with reduced insulin secretion by beta cells and whole-body insulin resistance by adulthood, although this conclusion is not unanimously accepted." (PMID 23383269, 2013). "Insulin is critical for the body’s use of GLU as energy, and insulin resistance (IR) is a condition in which the body produces insulin but does not use it effectively, leading to increased levels of GLU." (PMID 23967328, 2013). "Subsequently, the same research group demonstrated that TNFα suppressed insulin signaling by inhibiting insulin receptor tyrosine kinase activity and proposed a model in which inflammation defined as an increased level of TNFα in adipose tissue could be the basis of systemic insulin resistance." (PMID 23964268, 2013). "The insulin sensitivity index QUICKI was significantly lower in both the DYS and DM groups compared to the N group, while the insulin resistance index HOMA-IR was greater in the DYS and DM groups relative to the N group." (PMID 23886319, 2013). "In humans, in such conditions, insulin resistance is evaluated with the HOMA model and insulin sensitivity with the log-reciprocal QUICKI formula by using overnight fasting measurements." (PMID 23762879, 2013). "Whereas the classic target tissues such as muscle and fat manifest insulin resistance in PCOS, the ovaries of these patients remain sensitive to insulin or perhaps hypersensitive to it." (PMID 23599814, 2013). "The insulin sensitivity index (ISI, Matsuda–DeFronzo index) is an index of insulin resistance obtained from the glucose clamp technique and a 75-g oral glucose tolerance test (OGTT)." (PMID 23339473, 2013). "AR can be an important link between inflammation and insulin resistance, while MEF2A has role in insulin signaling." (PMID 24303025, 2013). "JNK activation is proposed to promote insulin resistance through upregulation of IRS serine phosphorylation, and IRS is a key common signaling component of both the insulin and IGF-1 pathways." (PMID 24252636, 2013). "Specifically, hyperglycemia is characterized by elevated hepatic glucose output and a defect in early insulin secretion, while IGT is characterized by peripheral insulin resistance." (PMID 24499585, 2013). "Correlations between insulin sensitivity, adiposity, and T2DM still remain to be fully revealed, even though resistin has been proposed as a potential link between obesity, insulin resistance, and T2DM with CVD." (PMID 24282409, 2013). "Using the fasting blood glucose, fasting insulin, and HOMA (homeostasis model assessment) score, the insulin resistance was found three times higher in an unselected population of women with recurrent pregnancy loss when compared with normal population." (PMID 24371440, 2013). "Due to these reasons the clinical on-set of T2DM appears later, because insulin-resistance in liver, adipose cells of the abdomen wall and skeletal muscles during the initial stage, i.e., for years or decades, may be balanced by increasing of the insulin secretion." (PMID 23447747, 2013). "Adenosine is involved in insulin mediated glucose uptake in skeletal muscle and high ADA activity tends to decrease glucose uptake into cells and thus contributes to insulin resistance." (PMID 24453844, 2013). "Expression of AIF-1 was inversely correlated with insulin sensitivity as assessed by insulin tolerance test (KITT), and circulating levels of adiponectin (P = 0.02), and positively correlated with insulin resistance as estimated by HOMA (=0.0042)." (PMID 24267103, 2013). "The most commonly used surrogate measure of insulin resistance is the homeostatic model of insulin resistance (HOMA-IR), which is a computation based on fasting insulin and glucose values." (PMID 24098646, 2013).
Insulin resistance (continued). "Insulin secretion in women with GDM is defective and, therefore, is unable to rise adequately to compensate for the insulin resistance; the result is hyperglycemia." (PMID 23805905, 2013). "Overactivation of mTOR/S6K cascade would exert a significant negative effect on the activity of downstream components of the insulin/PI3-K pathway, such as AKT, leading to insulin resistance." (PMID 24151517, 2013). "ER stress promotes LIPIN2-dependent hepatic insulin resistance and ERRγ is a novel transcriptional regulator of LIPIN1, and inhibits hepatic insulin signaling." (PMID 23716639, 2013). "One of the main barriers is psychological insulin resistance (PIR), defined as psychological opposition towards insulin use, among patients and healthcare providers." (PMID 24164794, 2013). "Our results show that 2-AA when injected into mice, induced a biological signature of insulin resistance as determined by 1H NMR analysis-, and dramatically altered insulin signaling, glucose transport, and mitochondrial function." (PMID 24098655, 2013). "Interestingly, Homeostasis Model Assessment of insulin resistance promises to be a valuable tool for primary prevention, particularly for patients with subclinical insulin resistance, presenting fasting plasma glucose levels and fasting plasma insulin levels in the normal range." (PMID 23497533, 2013). "The aim of this work was to evaluate H2O2 generation upon insulin stimulation and the possible involvement of NOX2 in the pathophysiology of insulin resistance." (PMID 23899788, 2013). "Under insulin resistance conditions, PI3K-dependent signaling pathways were selectively impaired, leading to endothelial dysfunction, which is characterized by a decrease insulin-mediated NO production and increased secretion of ET-1 from the endothelium." (PMID 23840461, 2013). "Given our observed increase in hepatic lipids with HFD, early insulin resistance likely occurred in liver and this would contribute to the impaired IPGTT result after 3 weeks of HFD despite insulin sensitivity in muscle." (PMID 23951235, 2013). "IGF-1 and insulin activate many of the same intracellular signaling pathways, and altered IGF-1 signaling has been demonstrated in states of insulin resistance." (PMID 24252636, 2013). "The progressively increase in serum insulin (hyperinsulinemia) and blood glucose (hyperglycemia) levels with HFFD considered as insulin resistance in rats." (PMID 23690866, 2013). "Insulin resistance was assessed using a homeostasis model assessment of insulin resistance (HOMA-IR), which is calculated from fasting blood glucose and insulin levels." (PMID 24069257, 2013). "TNF-α treatment in cell lines and rodents induces insulin resistance, and neutralization of TNF-α in obese fa/fa rats enhances insulin sensitivity." (PMID 23781214, 2013). "ERK1 is an important mediator of inflammation-induced insulin resistance, insulin receptor substrate (IRS)-1 serine (inhibitory) phosphorylation, and the inhibitory effect of TNFα on insulin signaling." (PMID 23431246, 2013). "A dysfunctional link between insulin and the targeting of GLUT 4 has been shown to contribute to insulin resistance." (PMID 23424590, 2013). "Furthermore, endothelial dysfunction associated to insulin resistance in obese subjects does not seem to rely on a defective vasodilatory action of insulin since, in contrast to BK-induced responses, insulin-induced vasodilatory responses were not different between MO subjects with or without IR." (PMID 24138787, 2013). "The coexistence of NAFLD and GI has been demonstrated to have a synergistic effect raising BMI, serum insulin and HOMA-insulin resistance (HOMA-IR)." (PMID 23688034, 2013). "Thus, this assumption might only explain the relation between insulin use and higher risks of liver cancer in those patients with insulin resistance, but not insulin-deficient patients." (PMID 23308218, 2013).
Insulin resistance (continued). "Homeostasis model assessment of insulin resistance (HOMA-IR) and insulin sensitivity indices (ISI) were calculated from the MTT results." (PMID 23339473, 2013). "Even in these younger women, body fat levels were associated with physiological indices of risk for T2D and cardiovascular disease, such as LDL cholesterol, CRP, blood pressure and insulin resistance (HOMA IR and fasting insulin), as well as WHR." (PMID 24376410, 2013). "As phosphorylation on this site produces blunt insulin signalling, the presence and action of JNK in facilitating this process further decrease insulin sensitivity and lead to insulin resistance." (PMID 24324517, 2013). "Finally, plasma concentration of adipose tissue metabolites, leptin and non-esterified fatty acids are higher and adiponectin levels are lower in insulin resistant Asian Indians as compared to more insulin sensitive Caucasians and could contribute to insulin resistance and atherogenic dyslipidemia." (PMID 23863826, 2013). "Waist circumference, blood pressure, HOMA insulin resistance (HOMA-IR) and plasma levels of fasting glucose, triglycerides, HDL cholesterol, LDL cholesterol, total cholesterol, insulin, and leptin were measured in the offspring." (PMID 23741411, 2013). "Because of a positive correlation between serum hsCRP and HbA1c, fasting insulin and HOMA-IR, inflammation, insulin resistance and hyperglycemia jointly contribute to the cardiovascular risk in type 2 DM men." (PMID 24360326, 2013). "In support of these findings, Tiganis and colleagues revealed that ROS can actually enhance insulin sensitivity and that mice with elevated ROS levels in various tissues can be protected against HFD-induced insulin resistance." (PMID 23460811, 2013). "In the present investigation, the elevation of glucose, insulin and HOMA in blood after the first bout of the stair descending exercise indicates the presence of insulin resistance." (PMID 23437093, 2013). "In our study, CD was found to increase serum glucose and decrease insulin sensitivity comparable with the HFC diet, which is known to induce insulin resistance in rats." (PMID 23434909, 2013). "Fifteen genes ranked among top 100 genes for obesity are also related to insulin sensitivity, NIDDM, insulin resistance." (PMID 24344781, 2013). "First, rats fed a high-fat diet develop insulin resistance and obesity, then low-dose STZ induced a mild impairment of insulin secretion that was similar to a feature of T2DM." (PMID 23829668, 2013). "In addition, it is important to note that insulin resistance was decreased significantly in the study group; however, the comparison between genders showed that the therapy was more effective to reduce insulin and HOMA-IR in males compared with female adolescents." (PMID 24285955, 2013). "GTCs supplementation was also found to decrease plasma levels of insulin, TNF-α, and IL-6 in a rat insulin resistance model." (PMID 22312273, 2012). "Fasting blood was taken to determine insulin, glucose, triglyceride and total, LDL and HDL cholesterol concentrations and homeostasis model-estimated insulin resistance (HOMAIR)." (PMID 22590532, 2012). "In order to better understand early effects of AAV5 Ex-4 treatment on the development of insulin resistance, insulin tolerance was tested (ITT) following an intraperitoneal insulin injection." (PMID 22808093, 2012). "In addition, an AEA-independent mechanism leading to insulin resistance may involve intramyocellular fat accumulation through its consequent elevated availability of lipid metabolites such as ceramides and diacylglycerols, which affect insulin signalling." (PMID 22823902, 2012). "We postulate that FWFE can alleviate insulin resistance via inhibiting the intracellular JNK inflammatory signaling cascades, restoring the PI3K-Akt/PKB insulin signaling pathway, and then enhancing glucose uptake in TNF-α-treated FL83B mouse hepatocytes." (PMID 22942720, 2012).